AURKB (aurora kinase B)
Diseases named in the same sentence as AURKB in open-access papers (continued):
Sharing a sentence is not in itself a finding about the gene and the disease.
lung carcinoma (continued). "Additionally, aurora kinase B-mediated phosphorylation and activation of CDCA8 plays a major role in human lung cancer." (PMID 35354488, 2022). "An investigational topoisomerase inhibitor, daurinol, in combination with radiation could effectively decrease lung cancer growth in xenograft mouse models through the inhibition of AURKA and AURKB." (PMID 33202573, 2020). "These authors demonstrated that using the dual AURKA and AURKB inhibitor, AI II, reduces growth, viability, and anchorage-independent growth in a KRAS-dependent manner, showing that AURKA and AURKB are promising targets for KRAS-induced lung cancer therapy." (PMID 33202573, 2020). "Furthermore, Survivin/BIRC5 interacted closely with molecules which were shown to regulate stem cell properties in lung adenocarcinomas (SPC25), influence radiosensitivity in lung cancer (AURKA), or mediate anti-EGFR therapy in NSCLC (AURKB)." (PMID 32039023, 2019). "As a highly selective inhibitor of AURKB, AZD1152 can overcome resistance to EGFR inhibitors in lung cancer via enhancing apoptosis, modulate paclitaxel response in non–small cell lung cancer, and enhance chemotherapeutic efficacy in pancreatic and colon cancers." (PMID 39927464, 2025). "As deregulation of AURKB is observed in different tumors, to test whether USP29 is a global regulator of AURKB, we analyzed AURKB protein expression in neuroblastoma SKN-BE2, lung cancer A549 and colorectal cancer HCT116 cells with or without USP29 depletion." (PMID 38233848, 2024).
leukemia (31 papers, 2012 to 2025). A malignant (clonal) hematologic disorder, involving hematopoietic stem cells and characterized by the presence of primitive or atypical myeloid or lymphoid cells in the bone marrow and the blood. "Aurora kinase B (Aurora B), a mitotic checkpoint kinase, has been found to be overexpressed in several types of leukemia." (PMID 34454635, 2021). "Pervious study has reported that inhibition of Aurora kinases induced apoptosis and autophagy in leukemia cells via AURKB/p70S6K/RPL15 axis with the involvement of PI3K/Akt/mTOR, AMPK, and p38 MAPK signaling pathways." (PMID 32194783, 2020). "Cellular experiments demonstrated that both inhibitors induced cell death with caspase activation and cell cycle arrest, however only the GW806742X inhibitor decreased with more efficacy AURKA and AURKB expression in K-562 leukemia cells." (PMID 33277547, 2020). "AURKB has been extensively investigated as a potential target in leukemia after it was discovered that AURKB was overexpressed in leukemia cells of acute lymphoblastic leukemia, acute myeloid leukemia and chronic lymphoid leukemia." (PMID 26460953, 2015). "Like the Rsk family, the Aurora kinase family consists of serine/threonine kinases commonly overexpressed in cancers, and overexpression of Aurora kinase B correlates with poor prognosis in several cancers, including ovarian, osteosarcoma, thyroid, prostate cancer, and leukemia." (PMID 40634321, 2025). "The amplification or overexpression of AURKB has been reported in leukemia and most solid tumors." (PMID 37079315, 2023). "AURKB inhibitors are in clinical trials for stages I-II leukemia." (PMID 33178836, 2020). "In a recent study, USP14, one of the proteasome-associated deubiquitinating enzymes, was found responsible for AURKB stabilization and AURKB stabilization by ectopic expression of USP14 prevented the apoptosis induced by chemotherapeutic drugs in leukemia cells." (PMID 30206236, 2018). "A dendrogram of leukemia patients clustered by hierarchical clustering in the BC CML and normal cell population showed that AURKA and AURKB were increased in BP CML patients compared with normal patients." (PMID 38714583, 2024). "Since the leukemia cell line K-562 was chemosensitive for both aurora kinase inhibitors (GW809897X and GW806742X), we decided to measure the AURKA and AURKB mRNA expression in the ALL patient’s blood cells." (PMID 33277547, 2020). "Employing the MAGeCK algorithm, this focused CRISPR screen unveiled COX4I1 (encoding Cytochrome c oxidase subunit 4 isoform 1) as a top essential gene in leukemia cells, alongside five previously reported leukemia essential genes (MYC, RPS6, CCND3, GAB2, and AURKB)." (PMID 39716856, 2025). "The first one refers to the pan-inhibitor of Aurora kinases danusertib, which has been shown to repress RPL15 signaling, notably negatively regulating the AURKB/p70S6K/RPL15 axis, and the effect leads to cell death (by apoptosis and autophagy) of human leukemia cells." (PMID 36838813, 2023). "Importantly, some of these genes have already been reported in relation to CML (e.g., AURKB, AZU1, HLA-B, HLA-DMB, PF4) and others have been found to play important roles in different leukemias (e.g., CDCA3, RPL18A, PRG3, TLX3)." (PMID 35008420, 2022). "The aim of this study was evaluated the mRNA expression profile of pediatric Acute Lymphoblastic Leukaemia (ALL) patients and the efficacy of two AURKA and AURKB designed inhibitors (GW809897X and GW806742X) in a leukemia cell line as a potential novel therapy for ALL patients." (PMID 33277547, 2020). "Mechanistic studies of MV4-11 leukemia cells and HCT-116 colon cancer cells revealed that DBPR114 modulated FLT3 and AURKA/B targets inside the cells and induced the accumulation of multinucleated cells, which indicates mitotic checkpoint override through AURKB inhibition." (PMID 35062934, 2022).
leukemia (continued). "Firstly, it was proved that non-selective AURKA and AURKB inhibitors GW809897X and GW806742X treatment reduced cell proliferation of leukemia cell line (K-562) with a potency constant IC50 of > 5 μM and 1.47 μM, respectively." (PMID 33277547, 2020).
gastric cancer (30 papers, 2012 to 2025). A primary or metastatic malignant neoplasm involving the stomach. "Deregulation of AURKB was observed in a variety of tumors, including gastric cancer, and its overexpression was associated with tumor progression and drug resistance." (PMID 38233848, 2024). "It has been reported that AURKB is linked to a poor prognosis in patients with chondrosarcoma, neuroblastomas, and gastric cancer." (PMID 38396874, 2024). "Through a mass spectrometry analysis of USP29 binding proteins, we identified USP29 as a novel AURKB deubiquitinase, which specifically deconjugates its K48-linked polyubiquitination and is crucial to AURKB stabilization in gastric cancer cells." (PMID 38233848, 2024). "For example, AURKB was found to be associated with the clinicopathological characteristics of gastric cancer, and its high expression activated the Wnt/β-catenin/Myc cascade to induce epithelial–mesenchymal transition." (PMID 36561847, 2022). "Single nucleotide polymorphisms (SNPs) of AURKB were associated with occurrence of gastric cancer (GC)." (PMID 31576249, 2019). "A number of studies discover that high expression of AURKB is associated with unfavorable prognosis of cancers such as acute myeloid leukemia, nasopharyngeal carcinoma, colorectal adenocarcinoma and gastric cancer." (PMID 27888627, 2016). "Furthermore, AURKB was overexpressed in gastric cancer and was strongly linked to clinicopathological features of the disease." (PMID 35354488, 2022). "Interestingly, in another study investigating the expression status of BUBR1 and AURKB, the authors concluded that overexpression of BubR1 and AURKB is associated with a low risk of gastric cancer progression." (PMID 22606061, 2012). "rs2289590 in AURKB might contribute to susceptibility for the development of gastric cancer." (PMID 31576249, 2019). "It has been shown that cyclin D (encoded by this gene) is, as a target of aurora kinase B (AURKB), a major factor that stimulates the proliferation of gastric cancer cells." (PMID 40005158, 2025). "Activation of USP29 by FUBP1 promotes the stability of AURKB and its oncogenic functions in gastric cancer." (PMID 39605891, 2024). "Previous studies reported that AURKB overexpressed in gastric cancer and promoted several malignant phenotypes including cell proliferation, metastasis and drug resistance." (PMID 38233848, 2024). "For example, AURKB accelerates the tumor growth of gastric cancer via activating the expression of cell cycle regulator CCND1 through pH3S10." (PMID 38713155, 2024). "Previous studies have reported the differential expression of the genes we identified in gastric cancer, but few studies have reported the differential expression of AURKB, CCNA2, PLK1, TPX2, and CDK1 in gastric cancer." (PMID 37238607, 2023). "For example, as a prognostic biomarker for gastric cancer, AURKB promotes the progression of gastric cancer through epigenetic activation of CCND1 expression." (PMID 37318676, 2023). "Convincing data have demonstrated the oncogenic action of AURKB in various cancers, such as gastric cancer and clear cell renal cell carcinoma." (PMID 36561847, 2022). "Barasertib is effective in the discontinuation of AURKB for the treatment of pediatric acute leukemia, and AURKB is also detected in many solid tumors, such as gastric cancer, glioblastoma, bladder cancer, and clear cell renal cell carcinoma." (PMID 33612479, 2021). "In addition, AURKB can promote the lymph node metastasis of gastric cancer and the invasion and migration of gastric cancer cells by targeting and regulating the expression of related genes." (PMID 38396874, 2024).
gastric cancer (continued). "Moreover, co-immunoprecipitation (Co-IP) using MGC-803 and HGC-27 cell lysates validated the specific interaction between endogenous USP29 and AURKB in gastric cancer cells." (PMID 38233848, 2024). "Silencing of AURKB may decrease the invasive and migratory capacities of gastric cancer cells by disrupting the VEGFA/Akt/mTOR and Wnt/-catenin/Myc pathways." (PMID 35354488, 2022). "AURKB promotes the proliferation of gastric cancer cells in vitro and in vivo." (PMID 35456460, 2022). "The results of this study revealed that AURKA (rs1047972 and rs911160), AURKB (rs2241909 and rs2289590) and AURKC (rs11084490) polymorphisms could affect the risk of gastric cancer, both individually and synergistically." (PMID 31521144, 2019). "In this study, SNPs rs2273535, rs1047972, rs911160 and rs8173 (AURKA), rs2241909 and rs2289590 (AURKB), rs758099 and rs11084490 (AURKC), and rs42873 (PLK1) mitotic kinases were screened for associations with the genetic susceptibility to gastric cancer (GC) in Bosnian population." (PMID 31521144, 2019). "It has been shown that AURKB can regulate the G2/M transition of cell cycle by activating the expression of CCND1 and CCNB1, thereby promoting the proliferation of gastric cancer cells." (PMID 38890303, 2024). "In terms of mechanism, USP29 is transcriptionally activated by FUBP1, and the deregulated USP29 interacts with and stabilizes AURKB, forming a FUBP1-USP29-AURKB axis that enables tumor cell proliferation and survival in gastric cancers." (PMID 38233848, 2024). "Our data for intronic rs2289590 in AURKB suggest that additional binding of the YY1 sequence-specific DNA-binding factor, when C allele is present within TF binding site, could modify AURKB expression level, which might result in higher susceptibility to gastric cancer occurrence." (PMID 31521144, 2019). "In this study, we reported that gastric cancer cells showed an accelerated G2/M transition promoted by CREPT/RPRD1B and Aurora kinase B (Aurora B)." (PMID 30518842, 2018). "In summary, our findings indicate that rhBNP-2 suppresses gastric cancer cell proliferation by inhibiting β-catenin and c-Myc with AURKA and AURKB expression to regulate inhibition of the cell cycle." (PMID 27636990, 2016). "Considering the important role of AURKB in controlling cell cycle, we reasoned that USP29 may promote gastric cancer cell proliferation by regulating cell cycle progression." (PMID 38233848, 2024). "AURKB phosphorylates MCAK at S192, thereby regulating migration and invasion of gastric cancer." (PMID 38890303, 2024). "To test this hypothesis, we ectopically expressed Flag-USP29 in gastric cancer cells and revealed that USP29 overexpression increased the AURKB protein levels." (PMID 38233848, 2024).
melanoma (25 papers, 2012 to 2026). A malignant, usually aggressive tumor composed of atypical, neoplastic melanocytes. "In another study, Aurora kinases were found to be implicated in melanoma resistance to T-cell cytotoxicity and combined treatment with Aurora kinase B inhibitor and ipilimumab led to significant tumor reduction in vivo." (PMID 35326726, 2022). "AURKB expression has been linked to therapy related drug resistance in different malignancies including vemurafenib-resistant melanoma, temozolomide-resistant glioblastoma, and epidermal growth factor receptor tyrosine kinase inhibitor-resistant NSCLC." (PMID 33915740, 2021). "Knocking down AURKB inhibited cell growth and induced apoptosis in melanoma, which was associated with the BRAF/MEK/ERKs and PI3-K/AKT signaling pathways." (PMID 32863956, 2020). "AURKB is overexpressed in melanoma, and the overexpression is associated with a reduced probability of survival of melanoma patients." (PMID 32863956, 2020). "Increased levels of AURKB have also been associated with activation of the MAPK pathway in melanoma, and furthermore application of the BRAF inhibitor vemurafenib, abrogated AURKB expression." (PMID 23110075, 2012). "The protein–protein interaction (PPI) network analysis identified hub genes such as MYC, BRCA1 and AURKB, which play critical roles in melanoma biology." (PMID 39823244, 2025). "As expected, the sensitivity of melanoma cells to hesperadin was positively correlated with AURKB expression." (PMID 37079315, 2023). "We report genome duplication in human melanocytic nevi, reciprocal expression of AURKB and microRNAs in nevi and melanomas, and rescue of arrested human nevus cells with AURKB expression." (PMID 34812139, 2021). "Diminished MIR211-5p/MIR328-3p expression concurrent with increased AURKB expression occurs in a substantial portion of melanomas." (PMID 34812139, 2021). "BRAFV600E has been previously demonstrated as an upstream activator of AURKB transcription in melanoma cells." (PMID 34812139, 2021). "After co-culture with autologous TILs, melanoma cells overexpressing AURKA or AURKB were more resistant to T-cell-mediated cytotoxicity, as evidenced by decreased comboscores." (PMID 33123754, 2021). "The changes in tumor volume and tumor weight confirmed a significant reduction in tumors with partial silenced AURKB in both vemurafenib-sensitive (A375) and -resistant melanoma (A375R)." (PMID 32863956, 2020). "In cell-based studies, we transfected shRNA lentivirus to knock down expression of AURKB in both vemurafenib-sensitive (A375 and M249) and vemurafenib- resistant melanoma cell lines (A375R and M249R)." (PMID 32863956, 2020). "In this study, we comprehensively studied the role and function of AURKB in melanoma, especially the interaction between AURKB and the BRAF/MEK/ERKs and PI3-K/AKT pathways." (PMID 32863956, 2020). "Flow cytometry results revealed that knocking down the expression of AURKB induced apoptosis in both vemurafenib-sensitive and -resistant melanoma cell lines." (PMID 32863956, 2020). "In this study, we examined the function of AURKB in the development of both vemurafenib-sensitive and vemurafenib-resistant melanoma." (PMID 32863956, 2020). "Overall, HI-511 mediates growth and apoptosis in both vemurafenib-sensitive and -resistant melanoma cells by targeting AURKB and BRAF V600E." (PMID 32863956, 2020). "We identified a unique role for AURKB in melanoma, through the mediation of both the BRAF/MEK/ERKs and PI3-K/AKT pathways." (PMID 32863956, 2020). "In summary, we showed AURKB to be a new target for both drug-sensitive and -resistant melanoma treatment." (PMID 32863956, 2020). "Immunohistochemical (IHC) analysis of the AURKB expression level in the normal skin and melanoma tissue array revealed that AURKB was overexpressed and significantly higher in melanoma." (PMID 32863956, 2020).